CRP (C-reactive protein)
Diseases named in the same sentence as CRP in open-access papers (continued):
Sharing a sentence is not in itself a finding about the gene and the disease.
diabetes (continued). "A meta-analysis on 28 RCTs (2961 patients) did not observe a significant benefit on CRP, TNF-alpha, or IL-6, while another systematic review with meta-analysis (SRMA) pooling 1617 diabetes patients from 28 RCTs reported lower CRP levels under a low GI regime." (PMID 40076626, 2025). "CRP affects periodontitis and diabetes by inhibiting osteoblast formation and promoting osteoclast formation through the PI3K/AKT signaling pathway, disrupting alveolar bone homeostasis." (PMID 39811802, 2025). "The nomogram prediction model constructed in this study, which incorporates independent risk factors such as diabetes, hemoglobin, serum PAF, IL-17, and CRP, can be integrated into clinical practice through a structured workflow." (PMID 40823570, 2025). "High levels of c-reactive protein improved the prediction of post-stroke delirium when also considering diabetes." (PMID 39860413, 2025). "In the univariate analysis, potential risk factors for PJI after THA included age, BMI, CRP, ESR, WBC, platelet count (PC), D-dimer, and diabetes (P < 0.05)." (PMID 40108055, 2025). "Covariates included age, gender, BMI, diabetes, hypertension, and CRP, selected based on clinical relevance and previous literature." (PMID 41323996, 2025). "Globally, higher intake of fiber leads to a significantly stronger reduction in CRP levels as shown by recent large RCT meta-analyses on the treatment of patients with diabetes or critical illness." (PMID 40076626, 2025). "Blood results indicated slightly elevated creatine kinase, C-reactive protein, and erythrocyte sedimentation rate levels, and poor diabetes control." (PMID 40922886, 2025). "Elevated PCT emerged as the strongest risk factor for hospitalisation, with additional predictors including advanced age (aged ≥65 years and per decade increase), hypotension, fever (>38°C), elevated CRP, creatinine (≥1.2 mg/dl), male sex, and diabetes." (PMID 40262850, 2025). "Cys C, Apo A, CRP, albumin, and GGT were identified as five potential biomarkers for evaluating the correlation between sleep score and the risk of diabetes complications." (PMID 40583046, 2025). "Benefits of zinc supplementation included decreased CRP, lipid and glucose levels as well as the management of hyperglycemia in diabetes." (PMID 41325371, 2025). "Hs‐CRP concentration was significantly lower in non‐diabetic subjects compared to patients with diabetes (p‐value < 0.001)." (PMID 40525652, 2025). "Between 2005 and 2010, research focused on metabolic biomarkers (e.g., homocysteine, C-reactive protein) and pharmaceutical care, reflecting the integration of early mechanistic insights with clinical guidance in diabetes management." (PMID 41141270, 2025). "From the results of this study, multivariate Logistic regression analysis identified diabetes, decreased hemoglobin levels, increased serum PAF and IL-17 levels, CRP as independent risk factors for intestinal obstruction in patients with radiation enteritis." (PMID 40823570, 2025). "Elevated concentrations of inflammatory markers, including C-reactive protein (CRP), interleukin-6 (IL-6), and tumor necrosis factor-alpha, have been consistently linked to cardiovascular disease, cancer, diabetes, obesity, and other metabolic disorders." (PMID 41228434, 2025). "It has been reported that PA is independently associated with pulse wave velocity (PWV) in peritoneal dialysis patients after adjusting for age, sex, diabetes, CRP, and eGFR." (PMID 40170053, 2025). "Univariate analysis revealed a significant association between preoperative C-reactive protein (CRP) value (p = 0.001) and preoperative diabetes history (p = 0.007) with PJI." (PMID 40363957, 2025). "Participants with diabetes had significantly higher hs‐CRP, IL1‐β, TNF, IL‐6 and IFG levels compared to the controls." (PMID 40525652, 2025). "Multivariate regression analysis revealed that diabetes mellitus, C-reactive protein levels, contrast volume, and elevated GGT serve as independent predictors of CIN." (PMID 40243457, 2025).
diabetes (continued). "The results of single-factor logistic regression analysis showed that age, hypertension, diabetes mellitus, lymphocytes, fibrinogen, D-dimer, C-reactive protein, serum amyloid A and HA were all statistically significant (P < 0.05)." (PMID 38390620, 2024). "Patients in C (7%) suffered more obesity, frequent comorbidities (hypertension, diabetes, chronic heart/lung/kidney diseases), poorer oxygenation, and even higher inflammatory biomarkers than B (neutrophils, D-dimer, procalcitonin, CRP)." (PMID 38915125, 2024). "Nine characteristics were determined using Lasso regression: globulin, G/A, diabetes, renal colic, hemoglobin, CRP, IL-6, urine bacterial count and HU value of effusion." (PMID 38896174, 2024). "In the single recurrent attack, there were significant differences in hypertension, diabetes mellitus, anemia, leukocytosis, CRP, white matter changes, and CMBs compared with the first-ever group or multiple recurrent attack group." (PMID 39407804, 2024). "Adjustments were made for sex and age (Model 1), cardiovascular risk factors (Model 2), and additionally for either BMI-category, s-IGFBP-1, HOMA-IR, diabetes, or hs-CRP." (PMID 38732147, 2024). "Model 2 was adjusted for Model 1 + marital status, race, education level, family income, smoking status, drinking, hypertension, coronary heart disease, stroke, diabetes, and C-reactive protein." (PMID 38243194, 2024). "The effect of Brazil nut and metformin on diabetes-instigated systemic inflammation was determined by measuring the serum CRP concentrations of the rats." (PMID 39239455, 2024). "So far, it has been described that elevated CRP values are influenced by factors such as diabetes, a sedentary lifestyle, smoking, and obesity." (PMID 39768734, 2024). "Patients with effectively managed diabetes (HbA1c levels below 7%) showed more rapid reductions in CRP levels and a reduced frequency of infection relapses." (PMID 39459635, 2024). "In the multiple recurrent attack group, there were significant differences in the distributions of sex, BMI, diabetes mellitus, anemia, leukocytosis, CRP, and decreased eGFR compared with the first-ever group or single recurrent attack group." (PMID 39407804, 2024). "Model 3 was adjusted for age, sex, marital status, PIR, education, smoking, BMI, hypertension, diabetes, asthma, coronary heart disease, stroke, carbohydrate intake, energy, protein intake, CRP, and total cholesterol." (PMID 39148702, 2024). "We found many previously reported associations, such as associations between leptin and sex and CRP and BMI, and also new associations that are biologically plausible, such as LIPL and LIPE with diabetes status." (PMID 38307861, 2024). "There were significant differences in age, sex, SBP, history of hypertension, diabetes, coronary heart disease, stroke, NC, lymphocyte counts, CRP, Alb, FPG, LDL-C, HDL-C, Hcy, eGFR, and UA between CSVD and non-CSVD groups (p < 0.05)." (PMID 39777309, 2024). "Patients with effectively managed diabetes (HbA1c levels below 7%) exhibited much quicker restoration of CRP levels and reduced osteoporotic remodeling durations in comparison to those with inadequately controlled diabetes." (PMID 39459635, 2024). "In almost all the studies examining the relationship between periodontitis and serum CRP levels, it has been emphasized that the individuals evaluated had systemic diseases such as diabetes, cardiovascular diseases, or rheumatoid arthritis." (PMID 38195732, 2024). "High CRP levels were correlated with a higher prevalence of sarcopenia when age, sex, marital status, race, educational level, BMI, hypertension, and diabetes were adjusted." (PMID 39969369, 2024). "In individualswith low ABIs, we observed a greater prevalence of diabetes mellitus, elevatedserum C-reactive protein (CRP) levels, increased galectin-3 levels, and lowerserum creatinine levels." (PMID 39076571, 2024).
diabetes (continued). "After excluding those with confounding factors for elevated CRP, 295 patients with concurrent diabetes, hypertension, or dyslipidemia were analyzed." (PMID 38983990, 2024). "These 10 key variables included smoking history, length of ICU stay, low protein levels, use of glucocorticoids, urinary catheterization, mechanical ventilation, CRP levels, diabetes, use of carbapenems, and use of β-lactamase inhibitors." (PMID 39403207, 2024). "Serum neuritin levels, GCS scores, hematoma volume, diabetes mellitus, blood C-reactive protein levels, and intraventricular hemorrhage significantly differed among seven groups, which were divided at a base of mRS (all p < 0.05)." (PMID 39839863, 2024). "Age > 70 years, smoking history, diabetes history, prolonged use of perioperative antibiotics, and elevated CRP, IL-6, and IGF-1 levels on the 1st day after surgery have an impact on postoperative lung infection in elderly patients with LC." (PMID 39495987, 2024). "For instance, as significant independent predictors of infection, Gnannt utilized diabetes, C-reactive protein (CRP), HU value of effusion, and intracavitary gas." (PMID 38896174, 2024). "Significant differences were observed for age, smoking status, body mass index, waist circumference, fat percentage, glucose, insulin, C-reactive protein, diabetes prevalence, lipid profiles, arterial stiffness, and blood pressure levels." (PMID 38218806, 2024). "The utility of salivary CRP extends beyond diabetes to encompass systemic and oral disorders, where it has shown promise as a biomarker for various medical conditions." (PMID 38741881, 2024). "In subjects with an HbA1c between 9 and 10.9%, there was a significant 215% increase in odds of having an average CRP concentration greater than 0.30 mg/dL when adjusted for demographics, smoking, BMI, fasting insulin level, and length of time with diabetes." (PMID 38999806, 2024). "Examining the effect of ω-3 fatty acids on CRP in individuals with diabetes is highly relevant, as CRP is an inflammation marker associated with elevated cardiovascular risk, particularly in diabetic patients." (PMID 39683500, 2024). "To ascertain the mortality risk between pleural effusion groups, we calculated HRs for different subgroups such as age, sex, cardiovascular disease history, diabetes, tuberculosis history, BMI, albumin, EF, CRP, RRF, D/Pcr and Kt/Vure at baseline." (PMID 38241413, 2024). "The most common comorbidities and altered laboratory results were hypertension, dyslipidemia, diabetes, as well as elevated levels of C-reactive protein, hemoglobin, and hematocrit." (PMID 38668001, 2024). "There were significant differences in age, systolic blood pressure (SBP), hypertension, diabetes, coronary heart disease, stroke, NC, lymphocyte count, CRP, Alb, FPG, Hcy, eGFR, and UA among the groups (p < 0.05)." (PMID 39777309, 2024). "The risk factors of spine infection with MSSA bacteremia included relatively lower rates of diabetes and higher CRP levels at onset and DISH compared to the other groups." (PMID 39619206, 2024). "Although the results of other conducted studies are inconsistent, they indicate that mothers with pre-pregnancy diabetes show abnormal pro–inflammatory protein/cytokine concentrations, such as IL–8, IL–6, CRP, TNF–α and IFN–γ." (PMID 38308265, 2024). "Patients with chronic inflammatory conditions such as cardiovascular diseases, diabetes, or autoimmune disorders often have elevated CRP levels." (PMID 39596303, 2024). "In both reactivation and coinfection groups, patients frequently report cardiovascular disease, diabetes, and immunosuppression as comorbidities, acute kidney injury as a complication, and lymphopenia and elevated D-dimer/C-reactive protein levels." (PMID 39861829, 2024). "Significant differences were found between the two groups in sex, age, race, BMI, CRP, hyperlipidemia, diabetes, hypertension, and physical activity (p < 0.05)." (PMID 39077156, 2024).
diabetes (continued). "Multivariate analysis revealed that age, diabetes, total albumin, SII > 752.6 × 109 and a CRP > 20.25 mg/L were independent risk factors for POD patients." (PMID 38566241, 2024). "To investigate the mechanism of elevated CA19-9 in the patients with diabetes, we screened subjects who were tested the CRP level and fasting C-peptide level for further statistical analysis." (PMID 38654232, 2024). "Statistical analysis results suggested that the age, proportion of cardiovascular disease, proportion of diabetes, NT-proBNP and CRP were higher, while BMI, serum albumin, EF and RRF were lower in the pleural effusion group." (PMID 38241413, 2024). "We determined that diabetes mellitus (OR = 3.305), high CRP (OR = 1.002), and high plasma IL-6 (OR = 1.045) were independent risk factors for ARDS-associated hypoactive delirium." (PMID 38523173, 2024). "In these groups, abnormalities in inflammatory markers, such as ESR and CRP, helped identify previously undiagnosed infections, while abnormal glucose levels led to the diagnosis of undiagnosed diabetes." (PMID 39594253, 2024). "To better understand the factors affecting the diagnostic accuracy of CRP, we evaluated CRP accuracy by HIV status, diabetes status and sex." (PMID 38712173, 2024). "Age, NYHA class, length of hospital stay, diabetes mellitus, a low concentration of hemoglobin and eGFR, a high level of CRP, and anxiety and depression scores were identified as significant predictors of frailty in the patients with HF." (PMID 39685803, 2024). "Noteworthy, among patients with diabetes, we noted an increase in performance for calprotectin, while those of CRP und procalcitonin both decreased." (PMID 38755564, 2024). "Spinal infection patients with MSSA bacteremia are less likely to have diabetes and more likely to have higher initial CRP levels and DISH." (PMID 39619206, 2024). "Salivary CRP has emerged as a promising biomarker for diabetes monitoring, with studies revealing a positive correlation between salivary and serum CRP levels in individuals with type 2 diabetes (T2D)." (PMID 38741881, 2024). "COPAVP and MRproANP were still significant (p < 0.05 each) when additionally sex, hypertension, diabetes, hyperlipidemia, log HbA1c, and log CRP were included as predictors (Model 3)." (PMID 38267944, 2024). "Another study also revealed lower levels of adiponectin and elevated CRP concentrations in adults with diabetes and cognitive impairment." (PMID 39409133, 2024). "A decrease in muscle strength is associated with a rise in inflammatory markers such as tumor necrosis factor-alpha (TNF-alpha), interleukin-6 (IL-6), and c-reactive protein (CRP), which can trigger the incidence of diabetes." (PMID 38276133, 2024). "Increased levels of CRP, an inflammatory marker in diabetes, exacerbate insulin resistance and diabetic cardiomyopathy through chronic inflammation." (PMID 39204151, 2024). "Diabetes can trigger an increase in cytokine levels leading to the production of C-reactive protein and fibrinogen." (PMID 38397350, 2024). "Compared to the HC group, the PD group showed significantly higher levels of hypertension, diabetes, neutrophil count, monocyte count, CRP, homocysteine, fibrinogen, and NLR." (PMID 39286804, 2024). "Elevated levels of inflammatory markers such as C-reactive protein (CRP) are associated with an increased risk of cardiovascular disease, metabolic syndrome, and type 2 diabetes mellitus (T2DM) in women with PCOS." (PMID 39201076, 2024). "Model 3 adjusted for age, sex, race, education level, poverty income ratio, body mass index, hypertension, diabetes, c reactive protein, high density lipoprotein, red blood cell, hemoglobin." (PMID 38431565, 2024). "The model comprising covariates (age, sex, hypertension, diabetes, cardiovascular disease, hemoglobin, platelets, serum creatinine, phosphorus, low-density lipoprotein and C-reactive protein) yielded an AUC of 0.771 (95% CI: 0.737–0.805, p < 0.001)." (PMID 38178381, 2024).
diabetes (continued). "Diabetes, advanced age, delayed reperfusion, low ejection fractions, congestive heart failure, elevated C-reactive protein (CRP) and brain natriuretic peptide (BNP) levels, and depression all contribute to a poor prognosis." (PMID 39156449, 2024). "As reported in the literature, Nrf2 protein level correlated with eGFR, proteinuria, diabetes mellitus, C-reactive protein (CRP), and SLEDAI score in renal diseases." (PMID 38304428, 2024). "Results were adjusted for natural log baseline CRP, age, sex, BMI, serious comorbidity (diabetes, cardiovascular disease, or hypertension), time and a treatment × time interaction." (PMID 39009040, 2024). "Lastly, higher calibrated MetaboHealth percentiles correlated with increasing age, BMI, high-sensitive CRP, and increasing prevalence of diabetes and alcohol usage." (PMID 39154540, 2024). "Adjustments were implemented in Model 3, which included hypertension, diabetes, chronic lung disease, CRP, HBA1c, TG, LDL-C, UA, Scr, Cystatin C, and TyG-BMI, as well as age, gender, smoking, and drinking status." (PMID 39606701, 2024). "Key predictors for mortality included factors like age, smoking, diabetes, cancer, chronic lung disease, past stroke, decreased left ventricular function, and elevated creatinine and C-Reactive Protein (CRP) levels." (PMID 38791012, 2024). "Elevated levels of high-sensitivity CRP, IL-6, and TNF-α were positively associated with the risk of microvascular complications in patients with diabetes." (PMID 39170741, 2024). "Inflammatory biomarkers CRP levels greater than 90.9 mg/L, and PCT levels greater than 0.307 ng/mL were significantly associated with the prevalence of diabetes-related hyperglycemic emergencies." (PMID 38455656, 2024). "Patients with PSCI were older, had higher high-sensitivity C-reactive protein levels, and were more likely to have hypertension, diabetes mellitus and education < 12 years." (PMID 39649719, 2024). "Those with gallstones exhibited higher age, BMI, CRP levels, and TyG values, a markedly elevated proportion of females, and a greater incidence of medical conditions, including diabetes, hypertension, coronary heart disease, cancer, and asthma." (PMID 38883189, 2024). "According to our results, one reason for prolonged hospitalization was elevated CRP levels among patients with diabetes." (PMID 38792970, 2024). "Of these, 7 patiens had hypertension, 4 of smoking, 4 of alcohol consumption, 1 of diabetes, 3 CRP abnormalities, 6 of Hs-cTnI abnormalities, and 5 of BNP abnormalities." (PMID 38347469, 2024). "A positive genetic correlation was also observed for abdominal aorta calcification, ischemic stroke, peripheral artery disease, body-mass index, diabetes and C-reactive protein." (PMID 38494474, 2024). "Other previously identified risk factors of AS in prospective studies are age, waist, BMI, CRP, smoking, diabetes, dyslipidemia, LDL cholesterol and Lp(a) levels." (PMID 39593205, 2024). "The levels of FFA and hs CRP in serum are closely related to type 2 diabetes and diabetes with coronary atherosclerotic heart disease." (PMID 39713052, 2024). "An observational study of 250 adults with uncontrolled diabetes on multiple oral hypoglycemic agents (OHAs) showed a reduction in highly sensitive-CRP (hs-CRP) and improvement in glycemic parameters with the addition of HCQ." (PMID 39273629, 2024). "Older age, longer length of hospitalization, duration of mechanical ventilation, tracheostomy, diabetes, and higher serum levels of C-reactive protein (CRP) and procalcitonin (PCT) at the time of intubation were associated with difficulty in oral intake." (PMID 38514734, 2024). "The study identified cardiovascular diseases, diabetes, obesity, dyspnea, lymphopenia, elevated ferritin, AST, and CRP as significant predictors and risk factors of ICU admission." (PMID 38572008, 2024).